MDP1 (magnesium dependent phosphatase 1)
Description:
Magnesium-dependent phosphatase which may act as a tyrosine phosphatase.
Synonyms: MDP-1; MGC5987; FN6Pase
Tractability: PROTAC: ubiquitination databases record sites on it; its protein half-life has been measured.
Gene: Protein-coding gene on chromosome 14 (24,213,943 to 24,216,070, reverse strand). Ensembl gene ENSG00000213920.
Subcellular location (Human Protein Atlas): Nucleoplasm
Gene Ontology:
Molecular function: acid phosphatase activity; phosphatase activity; protein tyrosine phosphatase activity
Genetic constraint (gnomAD): Loss-of-function variants: 19 observed, 24.31 expected, observed/expected ratio (o/e) 0.78, 90% interval 0.54 to 1.15. The upper end of that interval is the gene's LOEUF score, 1.15, which puts it in group 5 of 6, group 1 being the genes least tolerant of losing a copy. Missense variants: 207 observed, 229.64 expected, observed/expected ratio (o/e) 0.9, 90% interval 0.8 to 1.01. Synonymous variants: 101 observed, 88.72 expected, observed/expected ratio (o/e) 1.14, 90% interval 0.97 to 1.34.
Homologues: Orthologues: dog MDP1 (82% identical), rabbit MDP1 (81% identical), pig MDP1 (81% identical), chimpanzee MDP1 (60% identical).
Diseases named in the same sentence as MDP1 in open-access papers:
MDP1 is named in the same sentence as 7 diseases in open-access papers, as found by Europe PMC text mining. Sharing a sentence is not in itself a finding about the gene and the disease. The quoted sentences say what the papers report.
tuberculosis (5 papers, 2018 to 2024). A chronic, recurrent infection caused by the bacterium Mycobacterium tuberculosis. "Another gene associated with the risk of tuberculosis was MDP1, magnesium-dependent phosphatase 1, which has also been proposed to have a role in gastric cancer." (PMID 37108169, 2023). "In this study, we established a new method to purify recombinant MDP1, which adopted the predicted structure after this purification, and showed the usefulness of this recombinant protein in the development of a diagnostic test for asymptomatic tuberculosis." (PMID 30359374, 2018). "To evaluate the nature of recombinant MDP1 as a tuberculosis vaccine candidate, we obtained two types of monoclonal antibodies (mAbs)." (PMID 38644371, 2024). "Accordingly, our data show that the immune response to CFP10, ESAT6, Ag85 and PPD are higher while the immune response against MDP1 is lower in patients with active tuberculosis than in patients with past tuberculosis." (PMID 30359374, 2018). "MDP1 also induces the tolerance to isoniazid, a front line anti-tuberculosis drug, which is problemic characteristics of dormant M. tuberculosis." (PMID 30359374, 2018). "In contrast, when we used the equivalent protein purified by the current method, the background IgG reaction from healthy controls was decreased and the anti-MDP1 IgG level was significantly higher in past tuberculosis patients than in any other group." (PMID 30359374, 2018). "Furthermore, we showed that an IgG-ELISA using MDP1 purified by our refined method is indeed useful in the detection of asymptomatic tuberculosis." (PMID 30359374, 2018). "ELISA experiments revealed that rFull-MDP1, purified by the present method, may be useful for the diagnosis of asymptomatic tuberculosis." (PMID 30359374, 2018). "Although further evaluation of a combination of biomarkers is necessary, anti-MDP1 antibody may be a potential marker of asymptomatic tuberculosis." (PMID 30359374, 2018). "This implies that an evaluation of the ratio of immune responses to CFP10–ESAT6 and Ag85 vs MDP1 might be useful for determining the disease status of tuberculosis." (PMID 30359374, 2018). "By employing these strains, we observed that IDR of MDP1 is critical for MDP1-related phenotypes of M. smegmatis cell, including genome compaction, suppression of DNA synthesis, and drug tolerance to isoniazid, a front line tuberculosis drug." (PMID 29844400, 2018). "Both the IgG and T-cell responses to MDP1 are elevated in patients with asymptomatic tuberculosis, such as latent tuberculosis infection (LTBI) and past tuberculosis compared with that in patients with active tuberculosis." (PMID 30359374, 2018). "In fact, anti-MDP1 antibodies stained a lung biopsy sample derived from a person who had not developed tuberculosis." (PMID 30359374, 2018). "MDP1-IDR is also responsible for the induction of growth arrest and tolerance to isoniazid, a front line tuberculosis drug that kills growing but not growth-retardated mycobacteria." (PMID 29844400, 2018).
gastric cancer (3 papers, 2020 to 2023). A primary or metastatic malignant neoplasm involving the stomach. "Interestingly, the depletion of magnesium-dependent phosphatase 1 (MDP1) has been implicated as a poor prognostic factor in gastric cancer." (PMID 33057364, 2020). "Forced expression of MDP1 in the gastric cancer cell line BGC-823 inhibited cell proliferation, whereas the knockdown of MDP1 protein promoted cell growth." (PMID 33450887, 2021).
latent infection (2 papers, 2019 to 2024). "MDP-1 and Acr are known to be expressed during latent infection, which is believed to be beneficial for the survival of MTB." (PMID 38665909, 2024). "M. tuberculosis produces both Acr and MDP-1 during the latent infection." (PMID 31849981, 2019).
Granuloma (1 paper, 2012). A compact, organized collection of mature mononuclear phagocytes, which may be but is not necessarily accompanied by accessory features such as necrosis. "Since the fusion of macrophages and the formation of multi-nucleated cells is one of the hallmarks of chronic infections associated with granuloma formation we were interested in analysing the effect of MDP1 on macrophage fusion." (PMID 22863261, 2012).
myeloma (1 paper, 2024). "We immunized BALB/c mice with native MDP1 purified from BCG and screened for Ig-producing B cell hybridoma in lymph nodes and immortal myeloma cells." (PMID 38644371, 2024).
infection (5 papers, 2008 to 2023). The state of being infected such as from the introduction of a foreign agent such as serum, vaccine, antigenic substance or organism. "Mycobacterial DNA-binding protein 1 (MDP1) is a major protein in persistent Mycobacterium tuberculosis and has potential for diagnostic use in detecting asymptomatic infection." (PMID 30359374, 2018). "Multiple functions have been assigned to the MDP1 protein, but its precise role during the infection process has yet to be determined." (PMID 22863261, 2012). "Since we postulate the growth rate to be of major importance for virulence and intracellular persistence, we now investigated the role of MDP1 for the interaction of BCG with host cells during early phases of infection." (PMID 22863261, 2012). "Our study demonstrates that MDP1 fulfils various functions important for the infection of host cells and the maintenance of the infection within the granuloma." (PMID 18544159, 2008). "This suggests that MDP1 may be important in establishing infection and facilitating BCG in vivo survival." (PMID 37644087, 2023). "Taken together, these data suggest that MDP1 is an antigenic marker for asymptomatic infection." (PMID 30359374, 2018). "Further studies are required to find out whether MDP1 plays a role in adapting the gene expression pattern to the conditions occurring during the infection process." (PMID 18544159, 2008). "Our study aimed at defining the impact of the histone-like protein MDP1 from M. bovis BCG (mycobacterial DNA-binding protein 1, corresponding to Rv2986c from M. tuberculosis) on early steps of infection." (PMID 22863261, 2012). "MDP1/ML-LBP is a major cellular component of mycobacterial cell and is a multifunctional molecule depending on interaction with biomolecules, such as DNA, laminin, glycosaminoglycans, and glycolipids, and in turn controls gene expression, infection, and cell wall integrity." (PMID 21698192, 2011). "A large number of different functions have been proposed for the MDP1 protein from M. bovis BCG, but its role in infection has not been fully elucidated so far." (PMID 22863261, 2012).
MDP1 also shares sentences with these, for which no sentence is quoted: cancer (1 paper).